OTX2 (orthodenticle homeobox 2)
Diseases named in the same sentence as OTX2 in open-access papers (continued):
Sharing a sentence is not in itself a finding about the gene and the disease.
olfactory neuroblastoma (3 papers, 2020 to 2024). An olfactory neuroblastoma arising in the paranasal sinus. "In addition, OTX1 and OTX2 have been identified as two possible molecular markers for sinonasal carcinomas and olfactory neuroblastomas, whereas BACH2 is associated with the neuronal differentiation of N1E-115 neuroblastoma cells." (PMID 32391054, 2020). "In contrast, OTX2 is expressed in olfactory neuroblastomas and poorly differentiated neuroendocrine carcinomas." (PMID 39337467, 2024). "They identified the protein expression and the mRNA of OTX2 in olfactory neuroblastomas." (PMID 39337467, 2024). "Interestingly, only OTX‐1 was identified in non‐intestinal type adenocarcinomas, while OTX‐2 was selectively expressed only in olfactory neuroblastomas." (PMID 38925618, 2024).
retinal detachment (3 papers, 2016 to 2023). An eye emergency condition which may lead to blindness if left untreated. "In a previous study on samples of hypoxic retinal tissue from patients affected by proliferative vitreoretinopathy (PVR) secondary to retinal detachment, we observed an abnormal expression of both Otx1 and Otx2 associated with an increased severity of the disease in Otx2 expressing samples." (PMID 35003791, 2021). "The presence of OTX2 in differentiated cells of the retina is compatible with its role in cell identity maintenance, while its upregulation in PVR samples can be associated to the reactivation of proliferation in RPE cells released in the vitreous humor as a consequence of retinal detachment." (PMID 38069286, 2023).
amblyopia (2 papers, 2017 to 2024). Decreased vision that results from abnormal visual development. "Acute removal of Otx2 reactivates the plasticity for amblyopia in the adult cortex, suggesting a role for Otx2 as molecular brakes against critical period plasticity." (PMID 28974755, 2017). "Interestingly, transiently reopening plasticity by pharmacological OTX2 reduction in the adult cures experimental amblyopia in the mouse." (PMID 38550565, 2024).
bipolar disorder (2 papers, 2017 to 2021). A disorder of the brain that causes unusual shifts in mood, energy, activity levels and the ability to carry out day-to-day tasks. "Consistent with this, Otx2 mutations have been reported in people with such developmental disorders and polymorphism in Otx2 is a risk factor for bipolar disorder, whose etiology is also related to mitochondrial dysfunction." (PMID 28620275, 2017).
brain injuries (2 papers, 2021 to 2025). "Our study examined the role of Otx2 mRNA in the zebra finch brain following traumatic brain injury (TBI)." (PMID 40547083, 2025). "In turn, mutations of other transcription factors (e.g., PIT-1/POU1F1, PROP-1, LHX3, SOX2, SOX3, OTX2 and HESX1) lead to congenital MPHD, while hypothalamic-pituitary tumours (e.g., craniopharyngiomas), their treatment regimens or traumatic brain injuries result in acquired MPHD." (PMID 34445772, 2021).
breast carcinoma (2 papers, 2014 to 2015). "An alternative cause of OTX2 expression in these tumors would be that OTX2 is upregulated over the course of transformation through the acquisition of developmental or novel regulatory regions, as recently described for breast cancer or T-cell leukemia." (PMID 25198066, 2014). "Direct bisulfite sequencing also showed widespread methylation occurring in intragenic regions of the WT1, PAX6 and ITGA4 genes and in the promoter region of the OTX2 gene in breast cancer tissues." (PMID 26121976, 2015).
congenital hypopituitarism (2 papers, 2021 to 2022). "The authors identified three novel pathogenic variants in GHRHR, OTX2, and GLI2 expanding the spectrum of variants associated with congenital hypopituitarism." (PMID 36288632, 2022). "Like many other patients with congenital hypopituitarism, GHD is the most common endocrinopathy in patients with an OTX2 mutation, as seen in patients 1-10." (PMID 33950863, 2021). "We aimed to establish the contribution of OTX2 mutations in congenital hypopituitarism patients with/without eye abnormalities, study functional consequences, and establish OTX2 expression in the human brain, with a view to investigate the mechanism of action." (PMID 33950863, 2021).
COVID-19 (2 papers, 2023 to 2025). A disease caused by infection with severe acute respiratory syndrome coronavirus 2. "OTX2 shows the highest impact in blood, differentially regulating 142 genes out of 313 between COVID-19 and healthy samples." (PMID 37243274, 2023).
cyst (2 papers, 2013 to 2023). A sac-like closed membranous structure that may be empty or contain fluid or amorphous material. "To quantitatively assess the efficiency of retinal induction within our cyst cultures, we immunostained the cysts for the optic vesicle stage-related markers PAX6, RX, OTX2 and the optic cup stage-related marker CHX10." (PMID 23358448, 2013).
epilepsy (2 papers, 2014 to 2026). A brain disorder characterized by episodes of abnormally increased neuronal discharge resulting in transient episodes of sensory or motor neurological dysfunction, or psychic dysfunction. "Symmetrically, Otx2 rescues epilepsy and corticogenesis abnormalities in Otx1 knockout mice but fails to recover the lateral semicircular canal of the inner ear." (PMID 24558479, 2014). "Epilepsy-related proteins, including upregulation of GRM1 and COMT and downregulation of PDGFRB and OTX2, were noted." (PMID 41597222, 2026).
Ewing sarcoma (2 papers, 2014 to 2025). A small round cell tumor that lacks morphologic, immunohistochemical, and electron microscopic evidence of neuroectodermal differentiation. "In the analysis of H3K27ac ChIP-seq data from Ewing sarcoma (EWS), we find that BACH1, OTX2, and KNCH2 might affect EWS prognosis by binding to promoter and enhancer regions across the genome." (PMID 40210440, 2025).
glioma (2 papers, 2019 to 2024). A benign or malignant brain and spinal cord tumor that arises from glial cells (astrocytes, oligodendrocytes, ependymal cells). "In 2012, Wang reported that miR-206 regulated the proliferation of neural cells and its apoptosis through Otx2 in glioma." (PMID 31798345, 2019). "However, one study showed that OTX2 expression in gliomas was absent in five of twelve patients, low expression in six, and moderate expression in one." (PMID 38925618, 2024).
hypogonadism (2 papers, 2020 to 2024). A disorder characterized by decreased function of the gonads. "In particular, OTX2 targeted by ENSCHIT00000001255 could affect animal reproductive ability by promoting GnRH promoter activity in GnRH neuron cells, as OTX2 mutation was associated with hypogonadotropism." (PMID 33391342, 2020).
Microphthalmia, syndromic 5 (2 papers, 2018 to 2019). "Three distinct syndromic diseases are linked to haploinsufficiency of OTX2, namely combined pituitary hormone deficiency 6 (CPHD6, OMIM #613986), syndromic microphthalmia 5 (MCOPS5, OMIM #610125) and otocephaly/agnathia complex." (PMID 30268123, 2018).
microtia (2 papers, 2013 to 2023). "In our study, we identified one individual with an OTX2 mutation associated with unilateral microtia." (PMID 24498598, 2013).
mood disorder (2 papers, 2013 to 2021). A cognitive disorder a disturbance in which the person's mood is hypothesized to be the main underlying feature. "Otx2 is expressed in the brain, is involved in mood disorders and was identified in our previous study on long-term brain gene expression changes in FASD." (PMID 23580197, 2013). "We quantified mRNA levels corresponding to interneuron marker genes (PV and SST), plasticity genes known to be altered by OTX2 levels (Gadd45b, Arc, Nr4a1), and inflammatory/oxidative stress pathway genes (Mtnd4 and Iba1), given that mood disorders can be related to oxidative stress response." (PMID 33963285, 2021). "Furthermore, a number of genes identified have previously been implicated in FASD-relevant neurobehavioral phenotypes such as cognitive function, anxiety, attention deficit hyperactivity disorder and mood disorders (e.g. Otx2)." (PMID 23580197, 2013).
neuroblastoma (2 papers, 2020 to 2024). Neuroblastoma (NB) is the most common solid, extracranial childhood tumor. "Since our results showed relatively significant survival results, OTX‐2 may also be a predictive biomarker in neuroblastoma, but this protein needs to be further investigated in a larger sample size." (PMID 38925618, 2024). "OTX‐2 is a promising predictive biomarker candidate, but its mechanisms need further investigation in neuroblastoma, as nestin expression is not significantly linked to patient survival." (PMID 38925618, 2024).
retinitis pigmentosa (2 papers, 2023). Retinitis pigmentosa (RP) is an inherited retinal dystrophy leading to progressive loss of the photoreceptors and retinal pigment epithelium and resulting in blindness usually after several decades. "NRL mutations have been associated with retinitis pigmentosa and mutations in Blimp-1, RORβ, Otx2, Crx, or Nrl are associated with a loss of rod PRs in mammals." (PMID 36960411, 2023).
Alzheimer disease (1 paper, 2017). A progressive, neurodegenerative disease characterized by loss of function and death of nerve cells in several areas of the brain leading to loss of cognitive function such as memory and language. "Notably, expression of genes in mitochondria-related terms including “Alzheimer's disease” and “oxidative phosphorylation” are reported to be enriched in juvenile cortex and were all dysregulated in Otx2-deficient interneurons." (PMID 28620275, 2017).
autism (1 paper, 2025). Persistent deficits in social interaction and communication and interaction as well as a markedly restricted repertoire of activity and interest as well as repetitive patterns of behavior. "In doing so we identify variants that reproducibly alter the in vivo activity of OTX2 and MIR9-2 brain enhancers, implicating them in autism." (PMID 39762235, 2025).
B-cell lymphomas (1 paper, 2015). "While OTX1 expression has been described in small subsets of normal germinal center B-cells in addition to high levels in subsets of aggressive non-HL, OTX2 was detected neither in normal B-cells nor in B-cell lymphomas." (PMID 26406991, 2015). "However, this pathway did not contribute to OTX2 activation and requires more substantial investigation in this B-cell lymphoma–the HL cell line KM-H2 may represent a suitable tool for this purpose." (PMID 26406991, 2015).
cataract (1 paper, 2019). Partial or complete opacity of the crystalline lens of one or both eyes that decreases visual acuity and eventually results in blindness. "Because these Otx2-related mechanisms likely contribute to UV-triggered cataractogenesis, the present data clarify the pathogenesis of UV-related cataracts and other lens-related diseases and could be used to develop preventive treatments for cataract." (PMID 30718229, 2019).
CHARGE syndrome (1 paper, 2017). CHARGE syndrome is a multiple congenital anomaly syndrome characterized by the variable combination of multiple anomalies, mainly Coloboma; Choanal atresia/stenosis; Cranial nerve dysfunction; Characteristic ear anomalies (known as the major 4 C's). "The phenotypes of CHARGE syndrome show clear associations with defects in cranial NCCs, which prompted us to investigate the expression of OTX2, a cranial marker, by immunocytochemistry." (PMID 29179815, 2017).
colorectal cancer (1 paper, 2022). A primary or metastatic malignant neoplasm that affects the colon or rectum. "Novel transcription factors, such as OTX2, are discovered as critical factors for colorectal cancer." (PMID 35712778, 2022). "We successfully knocked down OTX2, RUNX1, MAZ,s and MAFK in HCT116 colorectal cancer cells, respectively." (PMID 35712778, 2022).
corneal dystrophies (1 paper, 2023). "Likewise, for COL8A1, an ECM component linked to AMD and to corneal dystrophies, 4 sites were bound by both OTX2 and LHX2 and 3 only by OTX2." (PMID 36649236, 2023).
diabetes (1 paper, 2024). "Further, we found a nominally significant difference in OTX2 DNA methylation between individuals with diabetic retinopathy and individuals with diabetes who did not have retinopathy based on a limited sample size." (PMID 38574408, 2024).
diabetic retinopathy (1 paper, 2024). "OTX2 is also related to eye health and an increase in OTX2 levels in mouse models has been shown to promote the survival of retinal ganglion cells, the loss of which leads to visual impairment in diabetic retinopathy." (PMID 38574408, 2024). "Both NGB and OTX2 have biological links to eye health, therefore we focused on investigating the association between DNA methylation at these two genes and diabetic retinopathy status in T2D cases." (PMID 38574408, 2024). "Three of the 20 T2D-DMPs reached genome wide significance at FDR 5% and were located in genes with possible links to diabetic complications such as blood pressure, cardiovascular disease and diabetic retinopathy (RGL3, NGB and OTX2)." (PMID 38574408, 2024). "Further analyses in a sample subset identified a nominally significant difference in methylation at one of the FDR 5% T2D-DMPs in OTX2 among individuals with T2D, between those with diabetic retinopathy and those without." (PMID 38574408, 2024).
Down syndrome (1 paper, 2019). "These images show comparisons between Down syndrome and normal fetal retinas for photoreceptors (RCVRN, OTX2) and bipolar cells (VSX2) amacrine cells (ELAVL3/4) and synapses (VGLUT/SLC17A7)." (PMID 30842553, 2019).
Failure to thrive (1 paper, 2009). Failure to thrive (FTT) refers to a child whose physical growth is substantially below the norm. "The history of early failure to thrive and subsequent short stature with low implied growth hormone levels adds further support for a role for OTX2 in pituitary function." (PMID 19956411, 2009).
Hyperglycemia (1 paper, 2016). An increased concentration of glucose in the blood. "Results showed that the expression of Pax6, Six3 and Otx2 were significantly inhibited by hyperglycemia, but other genes, such as Mitf, Rx1 and Chx10, were not affected significantly (data not shown)." (PMID 26744353, 2016). "In this model, the key genes regulating eye development, Pax6, Six3 and Otx2, were downregulated by hyperglycemia." (PMID 26744353, 2016). "Moreover, the Pax6 plasmid restored the expression of Six3 and Otx2 to levels that were nearly normal, suggesting that hyperglycemia-induced suppression of Pax6 is the upstream event." (PMID 26744353, 2016).
hypogonadotropic hypogonadism (1 paper, 2012). Abnormal ovarian or testicular function due to insufficient hormonal stimulation from the hypothalamic-pituitary axis. "Deficiency of Otx2 is responsible for human hypogonadotropic hypogonadism." (PMID 22761896, 2012).
hypothyroidism (1 paper, 2024). Abnormally low levels of thyroid hormone. "For instance, OTX2 Mutations have been linked to developmental abnormalities in both the central nervous system and the thyroid, resulting in hypothyroidism." (PMID 38877401, 2024).
Koolen-de Vries syndrome (1 paper, 2018). A chromosomal anomaly characterized by developmental delay, childhood hypotonia, facial dysmorphism, and a friendly/amiable behavior. "Notably, clinical refinement of complex phenotypes was achieved in 4 cases, including 2 de novo OTX2-related syndromes, a novel phenotypic association for the ciliary CEP41 gene, and the co-existence of biallelic USH2A variants and a Koolen-de-Vries syndrome–related 17q21.31 microdeletion." (PMID 29588463, 2018).
lens agenesis (1 paper, 2018). "SOX2 and PAX6 mutations may cause lens induction failure, FOXE3 mutations are associated with lens agenesis, and OTX2, CHX10, and RAX may cause failure of retinal differentiation." (PMID 30153864, 2018).
lymphoma (1 paper, 2015). A malignant (clonal) proliferation of B- lymphocytes or T- lymphocytes which involves the lymph nodes, bone marrow and/or extranodal sites. "We focused our study on OTX2 which may deepen our understanding and reveal undisclosed oncogenic function(s) in this heterogeneous type of lymphoma." (PMID 26406991, 2015).
macular pattern dystrophy (1 paper, 2024). "In conclusion, we present a case of OTX2-associated macular pattern dystrophy with megalopapilla, retinal vascular anomalies and relatively stable disease course." (PMID 39023660, 2024).
meningioma (1 paper, 2013). A generally slow growing tumor attached to the dura mater. "For the malignant meningiomas in our study, 26 genes were identified as significantly hypermethylated at promoter CpG islands, including eight genes involved in the biological pathway of neurogenesis (BARHL2, TLX3, FOXR1, HOXA11, HOXA6, HOXA9, OTX2 and PAX3)." (PMID 23349797, 2013).
otocephaly (1 paper, 2020). "The list of private protein-changing variants includes a de novo heterozygous nonsense variant in OTX2 (Chr7: 71478714G > A), a gene which is associated with otocephaly in people." (PMID 31969185, 2020). "The genetic findings were consistent with the diagnosis of the otocephaly and provide strong evidence that the identified loss-of-function variant is pathogenic due to OTX2 haploinsufficiency." (PMID 31969185, 2020). "While the knowledge on the causes of otocephaly in animals is limited, different syndromic forms in man are associated with variants of the PRRX1 and OTX2 genes." (PMID 31969185, 2020).
periodontitis (1 paper, 2023). An acute or chronic inflammatory process that affects the tissues that surround and support the teeth.
Photophobia (1 paper, 2021). Excessive sensitivity to light with the sensation of discomfort or pain in the eyes due to exposure to bright light. "Otx2 KO in PRs causes an arrestin-1 translocation defect associated with photophobia." (PMID 34475267, 2021). "We performed PR-specific Otx2 knock-out (KO) and found that removal of endogenous PR OTX2 leads to impaired arrestin-1 translocation associated with photophobia, specific modifications of PR and RPE gene expression, and to increased transfer of OTX2 protein from the RPE to the PR cytoplasm." (PMID 34475267, 2021). "In this manuscript entitled “Photoreceptor cKO of OTX2 enhances OTX2 intercellular transfer in the retina and causes photophobia", the authors studied the cell-autonomous function of the homeoprotein OTX2 in PRs by deleting specifically Otx2 in adult rod and cone PRs using Crx-CreERT2." (PMID 34475267, 2021).
pituitary deficiency (1 paper, 2024). "Despite some technical limits, CRISPR/Cas9-based genome editing of hiPSC is a powerful approach to elucidate gene function in congenital pituitary deficiency patients, as was shown for the role of hypothalamic OTX2 regulation of pituitary progenitor cells in congenital pituitary hypoplasia." (PMID 39607428, 2024).
prostate carcinoma (1 paper, 2024). A carcinoma that arises from epithelial cells of the prostate gland. "Little is known about OTX2 in the context of prostate cancer, though mRNA levels have been observed to be elevated in a small cell carcinoma prostate PDX model." (PMID 39349591, 2024).
prostate tumors (1 paper, 2025). "Both OTX2 and SREBP2 have been implicated in lineage plasticity of prostate tumors and are known regulators of C-MYC34–36, while TFDP1 promotes the proliferation and is frequently upregulated advanced disease." (PMID 40770488, 2025).
Shwachman-Diamond syndrome (1 paper, 2023). "In a cellular model of Shwachman–Diamond Syndrome (SDS), a rare ribosomopathy characterized by altered hematopoiesis, OTX2 has been found to be downregulated." (PMID 38069286, 2023).